INE1 (inactivation escape 1)
Synonyms: NCRNA00010
Gene: Long non-coding RNA gene on chromosome X (47,204,921 to 47,205,865, forward strand). Ensembl gene ENSG00000224975.
Diseases named in the same sentence as INE1 in open-access papers:
INE1 is named in the same sentence as 1 disease in open-access papers, as found by Europe PMC text mining. Sharing a sentence is not in itself a finding about the gene and the disease. The quoted sentences say what the papers report.
cervical cancer (1 paper, 2025). A primary or metastatic malignant neoplasm involving the cervix. "From this analysis, patients with advanced stages of cervical cancer were associated with the ATXN8OS marker, C5orf60 indicator, and INE1 index gene." (PMID 41300873, 2025). "Individuals with a recurrence of cervical carcinoma, a progressive disease, were associated with the ATXN8OS marker, the C5orf60 indicator, and the INE1 index gene." (PMID 41300873, 2025).